IGF1 (insulin like growth factor 1)
Diseases named in the same sentence as IGF1 in open-access papers (continued):
Sharing a sentence is not in itself a finding about the gene and the disease.
macrosomia (23 papers, 2010 to 2025). "Excessive energy intake, particularly during the final trimester, predisposes cows to fetal macrosomia by upregulating placental insulin-like growth factor 1 (IGF-1), increasing dystocia risk in primiparous heifers." (PMID 40141801, 2025). "Among participating mother-neonate dyad, maternal BMI at birth, neonate’s gender, and fetal cord serum IGF-1, and serum insulin were significantly associated with fetal macrosomia." (PMID 36001625, 2022). "Among participating mother-neonate dyad, maternal BMI at birth, neonate’s gender, and fetal cord serum IGF-1 and serum insulin are significantly associated with fetal macrosomia." (PMID 36001625, 2022). "The IGF-1/IGFBP-1 ratio was also positively associated with macrosomia in all four groups." (PMID 37685292, 2023). "IGFBP-2 and IGFBP-5 emerged as significant independent predictors of LGA birth in adjusted models (OR = 2.515 and 2.402, respectively; p < 0.001), consistent with prior studies linking first-trimester IGF-1 and IGF-1/IGFBP-1 ratios to macrosomia." (PMID 40943286, 2025). "Several authors have reported the role of insulin, IGF-1, and glucose in the determination of birth size, and by extension, fetal macrosomia in addition to fetal anthropometry." (PMID 36001625, 2022). "It is also uncertain what the contributions of IGF-1 and insulin are to fetal macrosomia in this setting." (PMID 36001625, 2022). "In this study, the level of IGF-1 was significantly higher in macrosomia compared to controls (85.09 vs. 53.94: p-value = 0.0001)." (PMID 36001625, 2022). "This increase in IGF-1 accessibility produces the enlargement of the placenta and thus, an extra nutrient supply to the fetus, promoting fetal growth and macrosomia, a characteristic detected in GDM pregnancies." (PMID 35813659, 2022). "Our study is the first in Nigeria to prospectively evaluate the relationship between IGF-1 and fetal macrosomia in euglycaemic mothers, thereby contributing to the growing evidence of the role of IGF-1 in growth and metabolic disorder in our environment." (PMID 36001625, 2022). "It showed that leptin (14.84±6.71 vs. 7.50±3.82, P = 0.008) and IGF-1 (93.20±56.88 vs. 51.99±22.19, P = 0.047) concentrations were elevated in fetal macrosomia." (PMID 29137266, 2017). "The levels of insulin-like growth factor-1 (IGF-1) were found to be associated with an increased risk of macrosomia in the presence or absence of maternal diabetes." (PMID 39062220, 2024). "It provides an association of IGF-1 and Insulin with fetal macrosomia in a largely non-diabetic population of pregnant women." (PMID 36001625, 2022). "At this stage, insulin and IGF-1 act as growth factors on fetuses resulting in macrosomia." (PMID 32708537, 2020). "Thus, elevated maternal IGF-1 and insulin levels from milk consumption may contribute significantly to the development of fetal macrosomia." (PMID 40357063, 2025). "Thus, the correlations between specific OTUs/phyla/genera and cord blood insulin, IGF-1 and leptin level may help to explain their roles in the development of fetal macrosomia." (PMID 29137266, 2017). "The purpose of this study was to assess the relationship between fetal insulin, insulin-like Growth factor-1(IGF-1), and macrosomia in a resource-limited setting." (PMID 36001625, 2022). "Studies comparing the placentas of women with and without GDM highlight the role of IGF-1 signaling in macrosomia." (PMID 40362828, 2025). "A study found that higher first-trimester IGF-1 and lower IGFBP-1 are associated with macrosomia in both diabetic and nondiabetic pregnancies." (PMID 37685292, 2023). "In addition, macrosomia, one of the complications of GDM, is related to the Insulin like growth factor 1 (IGF-1) axis." (PMID 36615730, 2022). "Also, the increased glucose, amino acids, and fatty acids assimilation observed in GDM placenta, stimulated endogenous fetal production of insulin and insulin-like growth factor-1 (IGF-1), which induced macrosomia." (PMID 31666083, 2019).
macrosomia (continued). "Thus, the binding of IGF-1 and IGF1R is promoted, so the PI3K/AKT pathway is over activated, leading to the increased transport of glucose to the fetus; as a result, there is the occurrence of macrosomia." (PMID 36615730, 2022). "Higher pregnancy weight gain could have arisen due to higher circulating IGF-1 that would have stimulated foetal growth, but HM IGF-1 did not correlate to infant birthweight in our cohort despite previous studies reporting increased HM IGF-1 concentrations with GDM and macrosomia." (PMID 31935821, 2020).
metastatic disease (23 papers, 2011 to 2025). "The IGF-binding protein domain of CYR61 is of particular interest because studies have reported that higher circulating levels of IGF1 are associated with metastatic disease and resistance to various chemotherapies." (PMID 41009559, 2025). "Since the members of the miR-29 and miR-30 family repress the IGF-1 signaling pathway, we explored the capacity of diet to alter metastatic tumor biology." (PMID 32211051, 2020). "In patients with high biopsy GS (196 with localized and 49 with metastatic disease), serum IGF‐1 levels for those with localized and for those with metastatic disease were not significantly different (139.6 vs 130.8 ng/mL, P = 0.260)." (PMID 29992746, 2018). "The number of metastatic tumors was significantly increased in IGF1 administrated KO tumor‐bearing mice, but the IGF1 treatment was unable to enhance the number of metastatic foci to the WT level." (PMID 26923183, 2016). "In the RCC cell lines including Caki-2 (from a primary tumor) and SK-RC-52 (from a metastatic tumor) IGF-1 was shown to enhance transforming growth factor-β (TGF-β) signaling and via TGF-β raise IGF-binding protein 3 (IGFBP-3) levels with growth-promoting effect." (PMID 27405474, 2016). "Similarly, among the 793 men with localized prostate cancer and 54 with metastatic disease, the inverse association between serum IGF‐1 level and risk of metastatic disease was no longer significant after adjustment for biopsy GS (Ptrend = 0.079)." (PMID 29992746, 2018). "Previously, liver-borne growth factors, IGF-1 and HGF were proposed to be predictors for metastatic disease and potential therapeutic targets for UM." (PMID 36551732, 2022). "Cell lines and metastatic tumor cells isolated from patients expressed IGF1R, and insulin-like growth factor-1 (IGF-1) activated the PI3-kinase/Akt and Ras/Raf/MAP-kinase pathways." (PMID 27437872, 2016). "In summary, there is substantial evidence regarding the critical role of IGF-1/IGF-1R signaling in the progression of PCa, with studies reporting correlations of IGF-1/IGF-1R with tumor cell proliferation, Gleason score, metastatic disease progression, and clinical outcomes." (PMID 36831629, 2023). "One recent study shows evidence for decreased IGF1 mRNA in local PCa compared to benign prostate, although IGF1 may still be involved in subsequent tumor progression as this study did not evaluate advanced or metastatic disease." (PMID 24708576, 2014).
renal fibrosis (23 papers, 2008 to 2026). A final common manifestation of a wide variety of chronic kidney diseases characterized by glomerulosclerosis and tubulointerstitial fibrosis. "Application of insulin-like growth factor 1 receptor (IGF-1R) inhibitor further confirmed that the regulation of autophagy and renal fibrosis by HDHW was associated with IGF-1-mediated activation of the PI3K/Akt/mTOR pathway." (PMID 36160409, 2022). "Baicalin therapy boosted insulin production and ameliorated renal fibrosis via activating the IGF-1/IGF-1R/p38 signaling pathway." (PMID 39911847, 2025). "This study has unveiled that overexpression of miR-483-3p inhibits the expression of IGF-1 protein, thereby promoting apoptosis in renal tubular epithelial cells and initiating renal fibrosis." (PMID 38972889, 2024). "Meanwhile, the expression of α-SMA was significantly up-regulated in the HDHW+JB1 group compared with the HDHW group (p < 0.001), indicating that the effect of HDHW in reducing renal fibrosis was related to the regulation of IGF-1 signaling." (PMID 36160409, 2022). "The results of the study showed that the inhibitory effect of HDHW on autophagy and renal fibrosis was altered after blocking the binding of IGF-1 to IGF-1R, and the phosphorylation processes of PI3K, Akt, and mTOR were also blocked." (PMID 36160409, 2022). "CD11b+/Ly6Clow M2 macrophages contribute to renal fibrosis by producing pro-fibrotic factors, including platelet-derived growth factor, insulin-like growth factor (IGF)-1, and CCL17, all of which are highly correlated with fibrogenesis or wound healing." (PMID 35990680, 2022). "Then, we treated HK-2 cells with TGF-β1 or GV114-IGF1 to examine the influence of IGF1 expression on renal fibrosis." (PMID 34707090, 2021). "We found that the administration of IGF-1 significantly reduced the severity of the renal fibrosis in UUO." (PMID 27301852, 2016). "Here, we found that the administration of IGF-1 significantly reduced the severity of the renal fibrosis in a mouse unilateral ureteral obstruction (UUO) model." (PMID 27301852, 2016). "Finally, insulin-like growth factor-1 (IGF-1) influences renal fibrosis through its effects on cell survival, proliferation, and matrix synthesis." (PMID 40141260, 2025). "This was accompanied by increased levels of insulin production with baicalin treatment, suggesting that baicalin may modulate the activation of the IGF-1/IGF-1R/p38 signalling pathway ameliorating STZ-induced renal fibrosis in DN rats." (PMID 39911847, 2025). "In addition, the results of the SR and fibronectin staining assays indicated more severe renal fibrosis in the crystallized kidneys after IGF1 antibody treatment." (PMID 38389846, 2024). "In STZ-induced diabetic mice, activation of IGF-1 promoted renal fibrosis by upregulating SNAI-1." (PMID 36225569, 2022). "In addition, elevated levels of IGF-1 activate the Akt signaling pathway, which expresses Snail1 and results in renal fibrosis." (PMID 36568065, 2022). "It was preliminarily concluded that IGF1 played a vital role in renal fibrosis." (PMID 34707090, 2021). "In addition, KLOTHO acts on TGF-β1 and inhibits insulin-like growth factor 1 (IGF-1) signaling pathways, thereby reducing renal fibrosis." (PMID 30208594, 2018). "IGF-1 has been shown to ameliorate renal injury and the subsequent development of renal fibrosis." (PMID 27301852, 2016). "Therefore, targeting the IGF-1/PI3K/Akt/mTOR pathway to inhibit the sustained activation of autophagy during renal fibrosis may be an appropriate approach for the treatment of renal fibrosis." (PMID 36160409, 2022). "In addition, IGF-1 decreases the activity of matrix metalloproteinase-2, an enzyme responsible for extracellular matrix degradation, thereby promoting extracellular matrix expansion and renal fibrosis." (PMID 23690758, 2013).
renal fibrosis (continued). "Notably, EAMs had a strong interaction with fibroblasts through the Igf1‐Igf1r signaling axis and IGF1 stimulated fibroblast activation and growth, suggesting its critical role in mediating the cellular interaction between macrophages and fibroblast in renal fibrosis." (PMID 39119903, 2024). "Impressively, the presence of kidney IGF1/CD68+ macrophage infiltration and the relevance of renal IGF1/CD68 expression to the degree of renal fibrosis were confirmed in human CKD." (PMID 39119903, 2024). "And further studies have shown that IGF-1, as a PI3K/Akt activator, improves renal fibrosis indicators in UUO rats." (PMID 36160409, 2022). "In conclusion, our study showed that HDHW inhibited autophagy by upregulating IGF-1 expression, promoting the binding of IGF-1 to IGF-1R, and activating the PI3K/Akt/mTOR signaling pathway, thereby reducing renal fibrosis and protecting renal function." (PMID 36160409, 2022). "In summary, our results indicate that BAI, and particularly the kidney-targeted BAI-LZM conjugate, produced inhibition of renal fibrosis and inflammation via the NF-κB, TGF-β1/Smad3 and IGF-1/p38 MAPK signaling pathways." (PMID 32398108, 2020). "The core genes SRC, IGF1, RHOA, ESR1, EGFR and CDC42 may play a key role in the inhibition of the development and progression of renal fibrosis by diosgenin." (PMID 37179298, 2023). "This suggests that HDHW activates the IGF-1/PI3K/Akt/mTOR signaling pathway, a key pathway in regulating autophagy, which further supports the regulatory effect of HDHW on autophagy in renal fibrosis rats." (PMID 36160409, 2022). "We hypothesized that HDHW could modulate the activity of the IGF-1/PI3K/Akt/mTOR pathway, inhibits autophagy and ameliorate renal fibrosis." (PMID 36160409, 2022). "The mechanism of HDHW ameliorating renal fibrosis may be that HDHW inhibits autophagy by upregulating IGF-1 expression, promoting the binding of IGF-1 to IGF-1R, and activating the autophagy-related pathway PI3K/Akt/mTOR, which in turn attenuate renal fibrosis." (PMID 36160409, 2022).
rheumatoid arthritis (23 papers, 2007 to 2025). A chronic, systemic autoimmune disorder characterized by inflammation in the synovial membranes and articular surfaces. "A meta-analysis of 27 rheumatoid arthritis clinical studies revealed that decreased serum IGF-1 levels were closely associated with the development of rheumatoid arthritis (RA), although the data varied considerably among studies." (PMID 41383600, 2025). "Since low insulin-like growth factor (IGF) 1 is often linked to inflammation, we analyze whether serum levels of IGF1 are associated with cardiovascular disease (CVD) in rheumatoid arthritis (RA) in a longitudinal observational study." (PMID 31327319, 2019). "Rheumatoid arthritis (RA) is associated with low muscle mass and density, and skeletal muscle of RA patients have been shown to have lower levels of IGF-1, which were associated with the severity of the disease, low appendicular lean mass, and lower myofiber CSA." (PMID 32858949, 2020). "The reasons for this are unclear as the subjects were otherwise in good health and while rheumatic heart disease is associated with reduced serum IGF-1, rheumatoid arthritis is not." (PMID 17974032, 2007). "Some patients with either rheumatoid arthritis (RA) or osteoarthritis (OA) have elevated serum GH but decreased serum IGF-1, when controlling for demographic characteristics such as age and BMI, suggesting GH signaling is associated with OA development." (PMID 38831184, 2024). "In this study we aim: 1) To study the presence of 192bp polymorphism of IGF-1 gene in patients of rheumatoid arthritis (RA), 2) To study the association of 192 bp polymorphism of IGF-1 gene with serum IGF-1 levels and disease severity in patients of RA." (PMID 37250538, 2023). "Another study has demonstrated that both serum and synovial fluid from rheumatoid arthritis (RA) could not stimulate chondrocyte proteoglycan synthesis once the IGF-1 function was blocked by a primary antibody." (PMID 34717735, 2021).
growth disorders (22 papers, 2012 to 2026). "These advancements position QAMS- as a robust tool for decentralized IGF-1 monitoring, particularly valuable in pediatric growth disorder studies and resource-limited settings." (PMID 41031093, 2025). "Insulin-like growth factor 1 (IGF1) is an important biomarker of human growth disorders that is routinely analyzed in clinical laboratories." (PMID 24278387, 2013). "Apart from identifying growth disorders, estimation of IGF-1 could also predict skeletal development in puberty to achieve favorable outcomes in orthodontic and orthognathic interventions." (PMID 35329407, 2022). "The reasons included suspected celiac disease and recent active weight loss (2 omnivore boys), consuming fish more than once a month (1 girl from the vegetarian group), and suspected growth disorder due to abnormal IGF-1 and growth hormone concentrations (2 vegan boys)." (PMID 33740036, 2021). "Measurement of insulin-like growth factor-1 (IGF-I) has utility for the diagnosis and management of growth disorders, but inter-assay comparison of results has been complicated by a multitude of reference standards, antibodies, detection methods, and pre-analytical preparation strategies." (PMID 22984427, 2012). "Insulin-like growth factors 1 and 2 (IGF-1 and IGF-2) are important biomarkers in research and diagnosis of growth disorders." (PMID 33569646, 2021). "Measurement of exact IGF-1 and IGFBP-3 serum levels has been widely used as a screening parameter in the assessment of growth disorders." (PMID 27738609, 2016). "Studies have shown that zinc supplementation improved serum insulin-like growth factor 1 (IGF-1) levels and promoted growth in infants born at term, with non-organic growth disorders." (PMID 35883555, 2022). "It has been demonstrated that GH, GHR, IGF-1 and IGF1-R coding sequences may be altered in growth disorders; however, these sequences are not changed in the genome of children with short stature and the search for other defective genetic backgrounds related to the IGF-1 axis should be considered." (PMID 25333772, 2014).